CTLA4 (cytotoxic T-lymphocyte associated protein 4)
Diseases named in the same sentence as CTLA4 in open-access papers (continued):
Sharing a sentence is not in itself a finding about the gene and the disease.
tumor (continued). "The study examines the use of next-generation checkpoints like LAG-3, TIM-3, TIGIT, IDO1, and VISTA to overcome resistance to CTLA-4/PD-1 inhibitors, particularly in GBM, where the immunosuppressive tumor microenvironment presents significant challenges." (PMID 40514725, 2025). "Humanised monoclonal antibody ICIs, including PD-1, CTLA-4, LAG-3 and TIM-3, target T cell immunoregulatory receptors utilised by tumours to suppress the immune response, promoting T cell mediated tumour recognition, cytotoxicity and death." (PMID 39859271, 2025). "CpG motifs in the promoter regions of immune checkpoint genes like PD-1, CTLA-4, and TIM-3 are less methylated in tumor tissue than in normal tissue." (PMID 40281554, 2025). "A top-down model was developed to illustrate tumor growth while coordinating radiotherapy with inhibitors targeting the PD1-PDL1 axis and the CTLA4 pathway." (PMID 40296809, 2025). "The strong correlation between ORAOV1 and aggressive tumor features, immunosuppressive TME, and poor response to anti-CTLA4/PD-1 therapy positions ORAOV1 as a dual-function biomarker suitable for prognostic stratification and treatment response prediction." (PMID 41321947, 2025). "Immune checkpoint inhibitors, including anti-CTLA-4, anti-PD1, and PD-L1, represent another immunotherapy group that targets immunosuppressive tumor environments." (PMID 40831543, 2025). "This suggests that co-blockade of PD-1 and CTLA-4 facilitates the entire process of T cells from activation to exercise of effector functions, whereas co-blockade of PD-1 and TIGIT provides enhanced tumor killing by activated T cells." (PMID 40890162, 2025). "CAN-2409 treatment resulted in significant tumor growth inhibition, comparable to combined CAN-2409/anti–CTLA-4 antibody treatment." (PMID 39881590, 2025). "This therapeutic effect was linked to the expansion and enhancement of effector and memory functions in tumor-infiltrating CD8+ T lymphocytes, along with a reduction in exhausted PD-1hi CTLA-4+ TIM-3+ CD8+ lymphocytes." (PMID 41024300, 2025). "Around tumor cells in stomach cancer models, you can find CD4+FoxP3− T cells, CTLA-4 T cells, and PD-L1 T cells." (PMID 40422244, 2025). "High expression of immune checkpoints, such as PD‐L1 (PDCD1LG2), TIM‐3 (HAVCR2), and CTLA‐4 (CTLA4), mediates inhibitory immune responses, thus facilitating tumor immune evasion." (PMID 40704619, 2025). "The vaccine group, the CTLA-4 siRNA-containing NLE group and the combination group all induced a significant increase in tumor-infiltrating CD8+ T cells compared to the PBS, naked mRNA, empty NLE, and isotype control groups." (PMID 40943370, 2025). "Several preclinical trials have demonstrated that the combination of PD-1/PD-L1 and CTLA-4 inhibitors has a significant synergistic effect in reversing cytotoxic CD8+ T cell exhaustion, attenuating the tumor load and prolonging survival." (PMID 40890162, 2025). "We observed that the numbers of Tbet+ICOS+ Th1-like CD4+ T cells in tumors correlated to reduced frequencies of CD45−CD31high tumor endothelial cells and increased frequencies of MECA-79+ TA-HECs after anti-CTLA-4 treatment." (PMID 40460830, 2025). "Immune checkpoint blockade therapies, which target immune cells expressing CTLA4,CD28,ICOS and PD1 in the tumor microenvironment, represents a first-generation antibody-based therapy for cancer." (PMID 40027134, 2025). "When anti-NKG2D antibody was co-administered with anti-CTLA-4 antibody in CT26-mock tumors, tumor progression occurred in a subset of mice." (PMID 40558520, 2025). "Aside from PD-1 and CTLA-4, chronic inflammation in TME can result in upregulated expression of several other IC receptors contributing to immunosuppression and resistance of tumor cells to the antitumor activity of lymphocytes infiltrating the TME." (PMID 40940764, 2025). "Cluster 1 exhibited higher TMB, tumor purity, and Ki-67, while Cluster 2 showed greater CD8+ T cells and elevated PD-1, PD-L1, and CTLA4 expression." (PMID 40612672, 2025).
tumor (continued). "A comprehensive analysis of ICPs revealed significantly higher levels of ICPs such as CD44, CD80, CD86, and CTLA-4 in the high-TKT expression group, thereby allowing tumor cells to evade immune surveillance, and facilitating tumor progression." (PMID 40230848, 2025). "FoxP3+ Tregs establish a robust immunosuppressive network by overexpressing checkpoint molecules (CTLA-4, PD-1, LAG-3) and secreting inhibitory cytokines (IL-10, TGF-β, IL-35), thereby creating an immune-privileged niche for tumor survival." (PMID 40563359, 2025). "In summary, PD-1 and CTLA-4 were primarily expressed in lymphocytes, whereas PD-L1 and LAG-3 were present in both tumor and lymphocyte cells." (PMID 40061944, 2025). "In recent years, tumour immunotherapy has expanded treatment options for patients with advanced NSCLC, with ICIs targeting PD-1, PD-L1, and CTLA-4 becoming a clinical hotspot." (PMID 39958820, 2025). "Tumor cells often exploit these immune escape mechanisms by expressing PDL1 and CTLA4, suppressing further anti-tumor immunity." (PMID 40427188, 2025). "Studies show that CD80 acts as a functional ligand for CTLA-4, particularly in tumour models where CD80-transfected tumours exhibit reduced immunogenicity compared to those with CD86." (PMID 40725864, 2025). "The USP24-specific inhibitor, USP24-i-101 alone or in combination with immunotherapy anti-CTLA4, profoundly reactivates T cell functions in the TME and markedly induces tumor inhibition." (PMID 40238877, 2025). "Other authors have reported that the flavonoid epigallocatechin is able to inhibit tumor cell growth via the PI3K pathway and can be used as a chemotherapeutic, a chemopreventive agent, or as combinatorial therapy with anti-CTLA4 against CRC." (PMID 40284221, 2025). "Although these therapies enhance tumor therapeutic efficacy, the majority induce more adverse effects than treatment with anti‐PD1 (aPD1) plus anti‐CTLA‐4 (aCTLA‐4) antibodies." (PMID 39606809, 2025). "The development of immune checkpoint inhibitors has resulted in significant breakthroughs in tumor treatment, with the most often employed immune checkpoints being PD-1, TIM-3, CTLA-4, LAG-3, CEACAM1, and TIGIT." (PMID 41326352, 2025). "For instance, tumor-reactive CD4+ T cells can induce tumor rejection in mouse models when transplanted and treated with anti-CTLA-4, demonstrating that cytotoxic CD4+ T cells can directly target and destroy tumor cells." (PMID 40177538, 2025). "By depleting CTLA-4-expressing Tregs in the TME via antibody-dependent cellular cytotoxicity, ipilimumab enhances anti-tumor immune responses and was the first immune checkpoint inhibitor to gain FDA approval in 2011." (PMID 40871003, 2025). "M1 macrophage-derived EVs similarly induce tumor death by decreasing the expression levels of CCR4, Foxp3, and CTLA-4 in canine peripheral mononuclear cells cocultured with tumor cells." (PMID 40530018, 2025). "The expression of CTLA4, PD-1, LAG3, and TIGIT has been correlated with NK cells exhaustion across various tumor types." (PMID 40688079, 2025). "Several gene signatures (FOXP3, Helios, neuropilin-1, CTLA-4, PD-1 and LAG-3) are also found to be upregulated in TIGIT+ Tregs within the tumor microenvironment (TME), turning Tregs to a more immunosuppressive phenotype." (PMID 40890162, 2025). "Considering that B68 can induce cellular senescence while reducing the expression of PD‐L1 in tumor cells and that combination therapy with anti‐PD‐L1 and anti‐CTLA4 has better therapeutic effects, we hypothesize that the combination of B68 with anti‐CTLA4 may further enhance B68 antitumor activity." (PMID 39721027, 2025). "Recently, the combination of CTLA-4 inhibitors and PD-1/PD-L1 inhibitors has been used to treat ES-SCLC, and has shown certain anti-tumor activity." (PMID 41415276, 2025). "In the literature, it has been shown that administering immunotherapy—especially CTLA-4 and PD-L1 inhibitors—concurrently with SBRT can enhance the anti-tumor immune response." (PMID 40283008, 2025).
tumor (continued). "In the same study, treating lung CSCs with a bispecific antibody targeting CTLA-4 and c-MET effectively inhibited cell proliferation and migration and reduced tumor volume in vivo." (PMID 41233805, 2025). "As immunogenic cell death signals have been shown to reduce intratumoral Treg populations, further investigation into the relationship between tumor GPX4 expression, anti-PD-1/CTLA-4 treatment, anti PD-L1/other ICI regimens, and Treg function is warranted." (PMID 40001204, 2025). "ICI therapies take effect by overcoming the inhibition of classic immune checkpoints, such as PD-1, PD-L1 and CTLA-4 on anti-tumor immune lymphocytes, particularly CD8+ cytotoxic T cells and NK cells, thereby reactivating bodies’ anti-tumor immune response." (PMID 40599775, 2025). "This condition is often characterized by increased levels of immune checkpoint molecules, such as PD-1, CTLA-4, and TIM-3, which hinder T-cell function and facilitate tumor immune evasion." (PMID 40066455, 2025). "CTLA-4 regulatory actions predominantly limit CD4 + T cell activation while promoting regulatory T cells (Tregs), resulting in a pro-tumor immunosuppressive phenotype." (PMID 39994019, 2025). "Combined with an anti-CTLA-4 antibody, this therapy remodels the TME, reduces Tregs and MDSCs, and increases CD8+ T-cells and cytokines like IL-12 and IFN-γ, enhancing tumor cytotoxicity." (PMID 40281554, 2025). "More importantly, in GC patients, TREM2+ TAMs exclude CD8+ T cell infiltration and promote immune checkpoint expression on tumor-infiltrated CD8+ T cells, like PD-1, CTLA4, and TIM3, which shapes an inhibitory immune microenvironment." (PMID 41253786, 2025). "Three distinct immunoscreening inhibitors, namely CTLA-4, PD-1, and PD-L1 inhibitors, have been approved by the FDA for the treatment of various tumor types." (PMID 40270890, 2025). "In detail, Kieffer and co-workers demonstrated that the abundance of ECM-producing CAFs and TGFβ-regulated CAFs in tumour samples is anticorrelated with CD8+ T cell infiltration but correlated with PD-1+ and CTLA4+ CD4+ T cell content in breast cancer." (PMID 41009413, 2025). "Immune checkpoint molecules such as CTLA-4 and PD-1, both members of the CD28 family, play central roles in tumor immunity." (PMID 40136375, 2025). "Conversely, upon CTLA4- or TGF-β-blocking immunotherapies or CD80 ablation, CSCs become vulnerable, diminishing tumour relapse after ACT treatment." (PMID 41009413, 2025). "Within the tumor microenvironment (TME), CD86 binds to CD28 and CTLA-4 on the surface of T cells, regulating T cell activation, proliferation, and survival." (PMID 41006647, 2025). "The targeted inhibition of immune checkpoints, such as CTLA4 and PD1, holds significant promise in managing OC, offering the potential to enhance anti-tumor immune responses and improve clinical outcomes for patients." (PMID 40427188, 2025). "Moreover, 9D9 mAb increased the proportion and absolute number of CD8+ T cells producing granzyme B. Thus, reduced Treg function and increased CD8+ T cell effector function could also contribute to the remodeling of the tumor vasculature and the increase of TA-HEVs during anti-CTLA-4 therapy." (PMID 40460830, 2025). "Several were most upregulated in specific subsets, such as multi-cytokine in CD8 memory; TIMD4/TIM3 in CD8 CM and γδT; CTLA4/CD38 in Treg, CD4 memory and CD8 CM; and OX40/EBI3 in tumor-infiltrating T cells." (PMID 40903640, 2025). "CTLA-4 deletion in CD19-CAR-T cells lifts inhibition of CD28 signaling under stress, enhancing proliferation, CAR expression, and anti-tumor efficacy in vitro and in vivo." (PMID 40672956, 2025). "CD8+ T cells, though critical for tumor cell lysis via IFN-γ and granzyme secretion, are often hindered by checkpoint molecules like CTLA-4 and PD-1, contributing to variable survival outcomes." (PMID 41007256, 2025).
tumor (continued). "CTLA-4 is another important immune checkpoint that binds to CD80 and CD86 on the surface of tumor cells and inhibits T cell activation." (PMID 40861450, 2025). "The elevated levels of lactate can further support the proliferation of tumor-infiltrating regulatory T cells (Tregs) and enhance Treg-mediated anti-tumor immunity, thereby decreasing the sensitivity of CRC to anti-CTLA-4 therapy (D9D)." (PMID 40264038, 2025). "Pro-tumor elements, such as regulatory T cells (Tregs) and MDSCs, create an immunosuppressive environment, inhibiting anti-tumor immunity via cytokines (TGF-β and IL-10) and immune checkpoint molecules (PD-L1, CTLA-4, TIM-3, TIGIT, and NRP1)." (PMID 40908470, 2025). "Recently, the comprehensive treatment of advanced‐stage tumours has increasingly relied on ICB agents targeting PD‐1/PD‐L1, CTLA‐4." (PMID 40845073, 2025). "Surprisingly, in addition to CTLA-4, anti-TIGIT inhibitors can also synergistically inhibit tumor growth in immunocompetent mice." (PMID 41236411, 2025). "Numerous transcripts related to immunological checkpoints, including SIGLEC15, PDCD1LG2 (PD-L2), TIGIT, PDCD1 (PD-1), CD274 (PD-L1), CTLA4, LAG3, and HAVCR2 (TIM3), are integral to tumor immune evasion mechanisms." (PMID 41194934, 2025). "In contrast to PD-1 or CTLA-4, BTLA forms a bidirectional signaling axis with its ligand, influencing not only T cells but also tumor cells and APCs." (PMID 41471273, 2025). "ICIs work by blocking inhibitory receptors such as PD-1, CTLA-4, NKG2A, and TIGIT, which are used by tumors to evade immune surveillance, thereby promoting more effective and durable anti-tumor responses." (PMID 39857739, 2025). "In sample HCC4, the tumor areas commonly expressed high IDO1, low PD‐L1 and CD274, and very low CTLA4." (PMID 41057994, 2025). "Trials targeting PD-1/PD-L1 (e.g., CheckMate 143) and CTLA-4 have demonstrated limited clinical benefit in unselected GBM populations, largely due to the profoundly immunosuppressive tumor microenvironment." (PMID 41179304, 2025). "For example, when combined with anti-CTLA-4 ICIs or another immunocytokines consisting of L19 fused with TNF-α, it led to complete tumor eradication in teratocarcinoma and colon carcinoma mouse models." (PMID 39852848, 2025). "Studies have found that in the TME of breast cancer patients, after Tregs bind to APCs via CTLA4, the expression of MHCII molecules on the APC surface decreases by about 30%, significantly reducing their ability to present tumor antigens to effector T cells." (PMID 41415289, 2025). "When tumor size reached ~100 mm3 volume, mice received 7.4 kBq of 225Ac-anti-CCR8 and a loading dose (10 mg/kg, 200 μg) of CTLA-4 immunotherapy." (PMID 41035646, 2025). "An in situ transplantation model showed that inhibiting CHI3L1 reduced tumor growth and downregulated MAF and CTLA4, while BCSCs increased S100A4 levels, further supporting the role of TN-BCSCs in immune escape." (PMID 40281554, 2025). "It has also been shown to reduce expression of immune inhibitory receptors such as programmed cell death protein 1 (PD-1) and CTLA-4 on CD8+ T-cells, thereby contributing to anti-tumor immune function." (PMID 41450919, 2025). "Exhausted T cells upregulate multiple inhibitory receptors (IRs), including PD-1, CTLA-4, TIM-3, LAG-3, and TIGIT, which bind to ligands on tumor cells and antigen-presenting cells (APCs), impeding T cell survival, expansion, and function." (PMID 40475782, 2025). "Hence, anti–CTLA-4 and anti–PD-1 combination therapy allows the emergence of autoreactive B cells that recognize self antigens expressed in tissues that are targeted by irAE and also by tumor cells, which may promote antitumor responses." (PMID 41026527, 2025). "We first compared side by side the vascular-modulating properties of anti-CTLA-4 mAbs 9D9 and 9H10, using a methylcholanthrene (MCA)-induced mouse tumor model (MCAprog) in which TA-HEVs spontaneously develop and mediate lymphocyte infiltration into tumors." (PMID 40460830, 2025).
tumor (continued). "Immune checkpoint markers are expressed on immune cells (i.e. PD-1, CTLA-4, CD25) and on tumor cells (PD-L1) and together inhibit immune cell activation and elimination of tumor cells." (PMID 40075112, 2025). "Univariate analysis revealed that diagnosis, preoperative treatment, tumor location, CD3+, CD8+, and Foxp3+ cell infiltration, as well as CTLA-4 and PD-1 expression, significantly impacted PFS." (PMID 39958339, 2025). "In a BLT humanized mouse model, combining anti-PD-L1, anti-CTLA-4, and anti-IFN-β reduced tumor growth by 96.2%, surpassing PD-L1/CTLA-4 inhibition alone (82.9%), by decreasing T-cell exhaustion markers." (PMID 41029427, 2025). "CTLA-4 is expressed on activated T cells and Tregs that suppresses T cell activation by binding to CD80/CD86 and enhances Treg activity in the tumor microenvironment." (PMID 39911397, 2025). "Another bifunctional TGF-β trap fused drug, anti-CTLA4-TGF-βRII, showed superior anti-tumour efficacy compared to an anti-CTLA4 antibody alone in preclinical models, but its efficacy in patients has not been investigated." (PMID 39780187, 2025). "In agreement with previous observations, we also observed changes in the phenotype of tumor-infiltrating Tregs upon treatment with anti-CTLA-4 mAb 9D9, suggesting that anti-CTLA-4 therapy reduces the activation, stability, and function of Tregs." (PMID 40460830, 2025). "Downregulation of AL031775.1 in T cells resulted in a significant decrease in T cell proliferation, an increase in apoptosis, and a reduced capacity for tumor cell lysis, accompanied by elevated expression of immune checkpoints LAG3, CTLA4, and PD1." (PMID 40066455, 2025). "Immune checkpoints such as PD-1/PD-L1, CTLA-4, LAG-3, TIM-3, and TIGIT play critical roles in regulating anti-tumor immunity and are exploited by hematological malignancies to evade immune surveillance." (PMID 40723175, 2025). "Cordycepin, combined with anti–CTLA-4 therapy, alleviated CD8+ T cell exhaustion in the tumor microenvironment by upregulating chemokine expression." (PMID 41244814, 2025). "In vitro pre‐activated T cells share main characteristics of antigen‐experienced T cells within the tumor microenvironment, such as upregulation of exhaustion markers PD‐1, TIM‐3, LAG‐3, and CTLA‐4 as well as enhanced IL‐12Rβ1 expression." (PMID 39981925, 2025). "Although immune checkpoint inhibitors such as PD-1/CTLA-4 have made breakthroughs in multiple cancer types, PDAC has not been able to overcome treatment challenges due to its highly immunosuppressive tumor microenvironment and inherent chemotherapy resistance." (PMID 41142819, 2025). "PSMB9 displayed strong correlations with classical inhibitory molecules such as LAG3, PDCD1, CTLA4, TIGIT, HAVCR2, SLAMF7, and PD-L1 across nearly all tumor types." (PMID 41020834, 2025). "This shift is evidenced by the upregulation of inhibitory receptors including PD-1, CTLA-4, LAG-3 and TIM-3, which results in T cell exhaustion and failure of their anti-tumour effector function." (PMID 39859271, 2025). "In murine anti-CTLA-4 models, butyrate impairs DC maturation and T cell ICOS expression, limiting expansion of tumor-specific and memory T cells and attenuating antitumor efficacy." (PMID 41339918, 2025). "A meta-analysis across 19 canine cancers found variable expression of PD-1, PD-L1, CTLA-4, LAG-3, and TIGIT, highlighting the relevance of personalized approaches due to tumor heterogeneity." (PMID 40725420, 2025). "They suppress anti-tumor immune responses through secretion of IL-10, IL-35, and TGF-β, and via expression of immune checkpoint molecules such as CTLA-4 and LAG-3." (PMID 41244711, 2025). "In Type II EOC, the “hot” immunophenotype of OC, particularly HGSC, IL6 is aggressively involved in driving immune evasion and tumor progression, such as upregulating immune checkpoint molecules, including PD1 and CTLA4." (PMID 40427188, 2025).